EPHA2 (EPH receptor A2)
Diseases named in the same sentence as EPHA2 in open-access papers (continued):
Sharing a sentence is not in itself a finding about the gene and the disease.
bone sarcoma (4 papers, 2021 to 2024). A sarcoma that arises from the bone. "In this protein family, Eph type-A receptor 2 (EphA2) has been identified as a driver oncoprotein in the pathogenesis of several tumors, including bone sarcomas, being implicated in the acquisition of self-renewal (stem cell-like) properties and metastasis." (PMID 34831119, 2021). "We previously showed that tyrosine kinase receptor Ephrin Type-A Receptor 2 (EphA2) is overexpressed in bone sarcomas." (PMID 39252029, 2024). "In bone sarcomas, EphA2 has come to the fore for its relevance to Ewing’s sarcoma tumor angiogenesis and metastasis." (PMID 34831119, 2021). "Aiming at better characterizing its expression throughout the main bone sarcoma histotypes, we investigated EPHA2 expression in the Cancer Cell Lines Encyclopedia and in public datasets with clinical annotations." (PMID 34831119, 2021). "In conclusion, EphA2 targeting represents a promising novel therapeutic strategy against bone sarcomas." (PMID 34831119, 2021). "In conclusion, EphA2 is overexpressed in the three main bone sarcoma histotypes and EphA2 targeting with a small-molecule inhibitor demonstrated significant antitumoral effects in all the tested patient-derived bone sarcoma cell lines." (PMID 34831119, 2021). "Furthermore, the EphA2 inhibitor showed significant antitumor effects in patient-derived bone sarcoma cells." (PMID 35163019, 2022). "Our PDXs could constitute a reliable platform to test different EphA2-targeting agents to strengthen preclinical data, in order to construct evidence for EphA2 targeting in clinical trials in different bone sarcoma histotypes." (PMID 34831119, 2021). "Furthermore, we tested the sensitivity of EphA2 higher vs. lower expressing primary bone sarcoma cell lines, against the EphA2 inhibitor ALW-II-41-27." (PMID 34831119, 2021).
cholangiocarcinoma (4 papers, 2011 to 2024). A carcinoma that arises from the intrahepatic biliary tree (intrahepatic cholangiocarcinoma) or from the junction, or adjacent to the junction, of the right and left hepatic ducts (hilar cholangiocarcinoma). "In cholangiocarcinoma, overexpression of EPHA2 enhanced AKT/mTOR signaling, thereby promoting the proliferation of CHO-CK cells in vitro and tumorigenicity in vivo." (PMID 33834064, 2021). "Regarding the events downstream of EphA2 S897, the Akt–mammalian target of ra-pamycin complex 1(mTORC1), Raf–MEK–ERK, and Pyk2–Src–ERK pathways were shown to be downstream effectors of the S897 EphA2 pathway in cholangiocarcinoma cells." (PMID 33572284, 2021).
chondrosarcoma (4 papers, 2021 to 2024). A malignant cartilaginous matrix-producing mesenchymal neoplasm arising from the bone and soft tissue. "In the study, tumor tissues of osteosarcoma, Ewing sarcoma, and chondrosarcoma showed higher expression of EphA2 compared to normal tissues." (PMID 35163019, 2022). "This represents an encouraging result for the chondrosarcoma histotype, in which EphA2’s role is a novel finding and which is particularly important given the current lack innovative therapeutic strategies." (PMID 34831119, 2021). "Patients affected by dedifferentiated chondrosarcomas (n = 16) with worse prognosis had significantly higher EPHA2 expression levels (p = 0.0091) compared to those with dedifferentiated chondrosarcomas, who experienced longer overall survival." (PMID 34831119, 2021). "We found EPHA2 gene expression in all but one of the four chondrosarcoma cell lines tested." (PMID 34831119, 2021). "Finally, for chondrosarcoma, we demonstrated abundant EphA2 expression at the tissue/protein level in our primary tumor samples and PDX models." (PMID 34831119, 2021). "Finally, EPHA2 was remarkably expressed in three out of four chondrosarcoma cell lines: CAL-78 (Z-score= 4.68), Hs 819.T (Z-score= 4.16) and SW 1353 (Z-score = 3.95)." (PMID 34831119, 2021). "Furthermore, for the first time, we demonstrated EPHA2 expression in chondrosarcoma, suggesting its potential key role in this histotype." (PMID 34831119, 2021). "Considering G3 conventional chondrosarcomas, EPHA2 expression was lower in the IDH1-mutated samples when compared to the IDH1 wild-type samples (* p < 0.05), while the opposite was observed with respect to the IDH2 mutations (higher EPHA2 expression in IDH2-mutated samples; * p < 0.05)." (PMID 34831119, 2021). "In the chondrosarcoma PDXs, the activated, phosphorylated form of EphA2, p-EphA2S897, was highly expressed, displaying functional non-canonical EphA2 pathway activation." (PMID 34831119, 2021).
colorectal tumors (4 papers, 2010 to 2023). "EPHA2 regulates tumour initiation, vascularization, tumour progression and metastasis, and immunohistochemistry in colorectal tumours indicated significantly higher expression of EPHA2 compared with matched non-tumorous (histologically normal) tissue." (PMID 36890818, 2023). "We also present initial evidence that EphA2 and TF are co-expressed in vivo in poorly differentiated colorectal tumors, thus warranting further studies on their cooperative role in human cancers." (PMID 27246245, 2016). "Higher mutation frequencies in the RTKs AXL (22%) and EPHA2 (17%) were detected in our panel compared to those reported in the TCGA database for primary colorectal tumors (3.51% AXL and 2.63% EPHA2)." (PMID 25193853, 2014). "Point mutations in EPHA2 and EPHA1 have not been specifically described in the literature for primary colorectal tumors, and lower mutation frequencies for these genes (4.4% EPHA1 and 2.6% EPHA2) were reported for primary colorectal tumors in the TCGA database." (PMID 25193853, 2014). "Furthermore, the efficacy of EphA2 antibody-based therapy may depend on tumor type as no suppressive effect on tumor growth was observed in a colorectal tumor model, whereas mice harboring ErbB2 in mammary epithelium were sensitive to therapeutic inhibition of EphA2." (PMID 20224755, 2010).
cutaneous melanoma (4 papers, 2011 to 2019). A primary melanoma arising from atypical melanocytes in the skin. "Additionally, VE-cadherin is colocalized with EphA2 at cell–cell adhesions and regulates EphA2 at the cell membrane in both uveal and cutaneous melanoma lines, by mediating its ability to become phosphorylated through interactions with its membrane bound ligand, ephrin-A1." (PMID 31212986, 2019).
intrahepatic cholangiocarcinoma (4 papers, 2021 to 2025). A carcinoma that arises from the intrahepatic bile duct epithelium in any site of the intrahepatic biliary tree. "A number of EphA2 mutations interfering with ephrin binding or kinase activity in cancer tissues such as intrahepatic cholangiocarcinoma (ICC) is being growingly recog-nized." (PMID 33572284, 2021).
liver cancer (4 papers, 2020 to 2024). An epithelial or non-epithelial malignant neoplasm that arises from the liver. "Suppressing EphA2 activity suppressed the development of sorafenib resistance in cultured cells and in mice with liver cancer, suggesting therapeutic possibilities." (PMID 32203105, 2020). "Similarly, in liver cancer, MIAT interacts with miR-520d-3p and miR-214, affecting EPHA2 and hepatoma-derived growth factor (HDGF) expression, respectively." (PMID 37624039, 2023).
microphthalmia (4 papers, 2021 to 2023). Congenital or developmental anomaly in which the eyeballs are abnormally small. "Even more recently, biallelic mutations in EPHA2 have been found in a syndromic form of microphthalmia with anterior segment dysgenesis." (PMID 36830662, 2023). "Heterozygous pathogenic EPHA2 variants have also been reported in two families presenting with congenital cataract and non-syndromic microphthalmia, widening the phenotype associated with this gene." (PMID 36830662, 2023). "A novel association of known cataract gene EPHA2 with microphthalmia was identified, and the remaining monogenic causes had been previously associated with MAC, although with previously unreported pathogenic variants." (PMID 36192130, 2023). "We therefore demonstrate a novel causative association of EPHA2 with microphthalmia." (PMID 33671840, 2021). "This study demonstrates a novel association of EPHA2 with microphthalmia, suggesting further analysis of pathogenic variants in unsolved microphthalmia cohorts may increase molecular diagnostic rates." (PMID 33671840, 2021). "The addition of EPHA2 to the microphthalmia, anophthalmia and coloboma (MAC)-targeted gene panels may aid diagnostics, and should be considered for screening unsolved microphthalmic cases." (PMID 33671840, 2021). "By including EPHA2 in routine genetic testing of microphthalmia, a greater proportion of patients may receive a molecular diagnosis, which can inform genetic counselling and guide clinical management, ultimately providing patients with enhanced clinical care." (PMID 33671840, 2021). "However, to the best of our knowledge, no mutations in EPHA2 have previously been associated with microphthalmia." (PMID 33671840, 2021). "However, no variants of EPHA2 have previously been reported in association with microphthalmia." (PMID 33671840, 2021). "However, EPHA2 is not typically found on microphthalmia, anophthalmia and coloboma (MAC) targeted gene panels, although it is included in cataract and lens-associated gene panels; hence, patients undergoing genetic testing may remain unsolved." (PMID 33671840, 2021).
myocardial infarction (4 papers, 2013 to 2021). Gross necrosis of the myocardium, as a result of interruption of the blood supply to the area, as in coronary thrombosis. "In addition, the EPH receptor genes EPHA2, EPHA8, and EPHB2 are located on chromosome 1 within region 1p34‐36, which has been identified as a locus for myocardial infarction by a genome wide search for susceptibility genes for myocardial infarction." (PMID 32337793, 2020). "When comparing healthy hearts with hearts representing acute myocardial infarction, significant downregulation of EGFR, ERBB2, ERBB3, as well as EPHA2, was discovered in the infarcted heart, ERBB2 demonstrating the greatest difference in expression." (PMID 30342492, 2018). "Analysis of RTK expression in the acute myocardial infarction samples revealed 4 RTKs with significantly reduced expression (EGFR, ERBB2, ERBB3 and EPHA2) when compared to healthy heart." (PMID 30342492, 2018). "Remarkably, EphA2+ human cardiac stem cells have been described to be dependent on this ephrin receptor to migrate in response to myocardial infarction, but it is not known if the stem cells described in this work derive from the epicardium, as suggested for other cardiac stem cells." (PMID 23349729, 2013).
Pendred syndrome (4 papers, 2020 to 2023). Pendred syndrome (PDS) is a clinically variable genetic disorder characterized by bilateral sensorineural hearing loss and euthyroid goiter. "Here we identify EPHA2 as another causative gene of Pendred syndrome with SLC26A4." (PMID 32165640, 2020). "Digenic inheritance of defects in SLC26A4 and EPHA2 has recently been reported in two Japanese Pendred syndrome cases." (PMID 34410491, 2022). "A recent report proposed a digenic inheritance of DFNB4/Pendred syndrome caused by monoallelic mutations in SLC26A4 and EPHA2." (PMID 34562878, 2021). "These authors found that EphA2 knockout mice showed an enlarged cochlear duct and thyroid hypertrophy, which are reminiscent of clinical features of Pendred syndrome." (PMID 34562878, 2021).
pneumonia (4 papers, 2018 to 2025). An acute, acute and chronic, or chronic inflammation focally or diffusely affecting the lung parenchyma, caused by an infection in one or both of the lungs (by bacteria, viruses, fungi, or mycoplasma.). "NOX4 and EphA2 levels were significantly higher in patients with pneumonia and especially in mechanical ventilated in the ICU." (PMID 35346198, 2022). "The NOX4 and EphA2 levels were significantly higher in patients with pneumonia compared with those in the control group." (PMID 35346198, 2022). "In patients with respiratory disease, NOX4 and EphA2 levels were significantly higher in patients with pneumonia and patients who received ventilator treatment in the intensive care unit." (PMID 35346198, 2022). "The NOX4 and EphA2 levels in BALF were investigated in patients with/without pneumonia." (PMID 35346198, 2022). "In addition, the relationship between EphA2 (which is related to lung injury) and NOX4 was investigated using EphA2 KO mice, and NOX4 and EphA2 levels in the bronchoalveolar lavage fluid (BALF) of 38 patients with pneumonia were examined." (PMID 35346198, 2022).
thyroid cancer (4 papers, 2015 to 2025). "Further the tyrosine kinase receptor EphA2, which has been found to mediate invasion in thyroid cancer, was downregulated in all treatment groups." (PMID 37803074, 2023). "Eleven of 18 BRAFV600E-specific genes were previously reported as related to thyroid cancer, with 6 documented as associated with BRAF mutation (DCSTAMP, MET, FN1, DIO1, EPHA2, and ERBB3)." (PMID 26625260, 2015).
acute myeloid leukemia (3 papers, 2015 to 2024). Acute myeloid leukemia (AML) is a group of neoplasms arising from precursor cells committed to the myeloid cell-line differentiation. "The decreased expression of CEACAM1 and EPHA2 was found to be associated with several cancers, but ITGB5 reduction in expression was associated with acute myeloid leukemia (LAML) only." (PMID 34908921, 2021).
adenoid cystic carcinoma (3 papers, 2014 to 2025). A malignant tumor arising from the epithelial cells. "On the other hand, there is a recent study showing that not only EphA2 but also ephrinA1 was highly expressed in adenoid cystic carcinoma and correlated with tumor invasion." (PMID 24606764, 2014). "A previous study has reported a correlation between EPHA2/EFNA1 expression and perineural and vascular invasion in Adenoid Cystic Carcinoma." (PMID 40075699, 2025). "In another study, EFNA1/EPHA2 was correlated with TNM stage and perineural invasion in adenoid cystic carcinoma of the salivary glands." (PMID 37719704, 2023). "We report a case of adenoid cystic carcinoma with perineural spread and provide the first published evidence that EphA2 expression without ephrin-A1 and epithelial–mesenchymal transition might play important roles in adenoid cystic carcinoma progression." (PMID 24606764, 2014).
angiosarcoma (3 papers, 2010 to 2020). A malignant tumor arising from the endothelial cells of the blood vessels. "On the other hand, expression of PDGFRβ, CD44, and EPHA2 in hemangiosarcoma cell lines was not predictive for the expression of these proteins in tumor tissues, and a similar trend was observed for Neuropilin 1 and v-Myc." (PMID 21062482, 2010).
cerebral malaria (3 papers, 2020 to 2025). A sequestration of Plasmodium falciparum in the brain, which can cause coma and/or seizures. "This breakthrough identifies EphA2 as a critical mediator of neurovascular injury and a compelling potential therapeutic target in cerebral malaria." (PMID 41002937, 2025). "Blocking EphA2 protects against BBB breakdown highlighting EphA2 as a potential therapeutic target for cerebral malaria." (PMID 31999807, 2020). "Furthermore, EphA2 is necessary for CD8+ T cell brain infiltration and subsequent BBB breakdown in a mouse model of cerebral malaria." (PMID 31999807, 2020).
cervical tumor (3 papers, 2022 to 2024). "To investigate whether EphA2 can also regulate the expression of CXCL11 and PD-L1 in vivo, we established the xenograft cervical tumor model." (PMID 36478746, 2022).
chronic myelogenous leukaemia (3 papers, 2015 to 2025). "Dasatinib is an oral dual Bcr/Abl and Src family kinases inhibitor approved for treating patients with chronic myelogenous leukaemia and has been shown to have significant activity against EphA2." (PMID 40615663, 2025).
fungal infections (3 papers, 2020 to 2025). "On the other hand, assessment of CR3-deficient mice has elucidated the compelling action of beta-glucans in neutrophil-mediated fungal clearance, and the investigation of EphA2-deficient mice has highlighted its novel involvement in host sensing and defense to oral mucosal fungal infection." (PMID 33946381, 2021). "In OECs, EphA2 is a receptor that participates in β-glucan recognition, triggering the production of pro-inflammatory mediators in response to fungal infections." (PMID 40233931, 2025). "The role of the EphA2 receptor in the transport of C. neoformans over the blood–brain barrier and the importance of EphA2 activation for the antifungal activity of neutrophils highlights the important role of EhpA2 in fungal infections." (PMID 33123097, 2020).
head and neck squamous cell carcinoma (3 papers, 2014 to 2025). A squamous cell carcinoma that arises from any of the following anatomic sites: lip and oral cavity, nasal cavity, paranasal sinuses, pharynx, larynx, and salivary glands. "In head and neck squamous cell carcinoma (HNSCC), knocking down EphA2 in vitro leads to a reduction in the number of VM channels, and the expression of EphA2 and EMT-related markers such as Twist and Vimentin expression have a positive association." (PMID 32169087, 2020).
ischemic stroke (3 papers, 2013 to 2023). A stroke disorder caused by obstruction of blood flow to the brain, due to thrombotic (local blood clot formation) or embolic (due to a blood clot or other material traveling from another site) event. "The activation of EphA2 receptor by its natural ligand EphrinA1 causes blood brain barrier dysfunction, and inactivation of EphA2 reduces BBB damage in ischemic stroke." (PMID 28507312, 2017). "In order to confirm expression of EphA2 and its ligands in cortical neurons, and to evaluate their role in ischemic stroke-induced neuronal death, we first performed confocal imaging." (PMID 23308246, 2013). "Immunoblot analysis of the protein lysates indicated significantly lower levels of cleaved caspase-3 in neurons from EphA2−/− compared to WT mice, consistent with a direct contributing role of the EphA2 receptor to neuronal cell death following ischemic stroke." (PMID 23308246, 2013). "However, EphA2 contributes to brain blood barrier damage and neuronal death after ischemic stroke." (PMID 37179400, 2023). "Hence, targeted blockage of EphA2 activation may protect BBB in ischemic stroke." (PMID 28507312, 2017).
meningioma (3 papers, 2020 to 2025). A generally slow growing tumor attached to the dura mater. "In meningiomas, aberrant activation of EphA2 and EphB1 promotes proliferation through engagement with mTOR and ERBB3 signaling pathways." (PMID 41200151, 2025). "In NF2-null meningioma cell lines, kinome profiling revealed activation of Eph receptor tyrosine kinases (EphA2, EphB1), c-KIT, and the Src/SFK pathway, targets of the FDA-approved kinase inhibitor Dasatinib." (PMID 41200151, 2025). "Moreover, EPHA2 and EPHB1 are overexpressed in neurofibromatosis type 2 gene (NF2) deficient meningiomas, and their pharmaceutical targeting with Dasatinib favors patients’ prognosis." (PMID 38612645, 2024).
metastatic cancers (3 papers, 2004 to 2021). A carcinoma which has spread from the original site of growth to another anatomic site. "A novel tyrosine kinase receptor EphA2 is expressed at high levels in advanced and metastatic cancers." (PMID 15563374, 2004). "Patient C008 contained an actionable mutation in EPHA2 (p.R762H, COSM3782397), suggesting that this patient might benefit from receptor tyrosine kinase inhibitors in metastatic cancer." (PMID 34070951, 2021).